VDR (vitamin D receptor)
Diseases named in the same sentence as VDR in open-access papers (continued):
Sharing a sentence is not in itself a finding about the gene and the disease.
disc degeneration (10 papers, 2016 to 2025). "Subgroup analysis by Pfirrmann grade showed an association between higher circulating VDR and advanced disc degeneration (Pfirrmann grades 4 and 5)." (PMID 40244065, 2025). "According to the previous literature, disc degeneration is associated with polymorphisms in several genes, such as the Vitamin D Receptor (VDR) and cytokines, which suggests that it is a multi-genetic condition." (PMID 37371064, 2023). "In previous studies, the relation between VDR TaqI gene polymorphisms and disc degeneration was investigated." (PMID 35919638, 2022). "There was a significant association between VDR ApaI mutation and risk of disc degeneration and subgroup analyses by ethnicity showed a significant association in Caucasians and in Asians." (PMID 34011063, 2021). "After that a series of studies with limited sample sizes have explored the association between VDR gene polymorphisms and disc degeneration risk, but the results still remain controversial." (PMID 34011063, 2021). "There was a significant heterogeneity between VDR FokI polymorphism and risk of disc degeneration except in Recessive model: Heterogeneity chi-squared = 21.26 (d.f. = 15) P = .129, I-squared = 29.4%." (PMID 34011063, 2021). "As the previous studies have generally been small-sized, several meta-analysis have been performed to explore the association between VDR gene polymorphisms and disc degeneration risk." (PMID 34011063, 2021). "The subgroup analyses by ethnicity showed a significant association of VDR FokI mutation with disc degeneration risk in Caucasians (recessive model, OR with 95%CI 1.301, [1.041, 1.626]; additive model, OR with 95%CI 1.119, [1.006, 1.245])." (PMID 34011063, 2021). "Summary of the meta-analysis results for the association between VDR gene polymorphisms and risk of disc degeneration." (PMID 34011063, 2021). "There was a significant heterogeneity between VDR FokI polymorphism and risk of disc degeneration except in Recessive model: Heterogeneity chi-squared = 8.21 (d.f. = 6) P = .223, I-squared = 26.9%." (PMID 34011063, 2021). "In summary, based on the most updated information, we drew a more reliable conclusion on the influence of VDR gene polymorphisms on disc degeneration." (PMID 34011063, 2021). "Some authors explored the association between VDR TaqI, BsmI, ApaI and FokI polymorphisms and disc degeneration, however the results were conflicting." (PMID 29467039, 2018). "Investigators further observed a significant association (p<0.001) between TT and FF genotypes of the VDR gene and mild forms of disc degeneration." (PMID 30356314, 2018). "Although a link between vitamin D receptor (VDR) gene variants and disc degeneration-related pathologies has been observed, its functional contribution to pathologic processes has not been assessed yet." (PMID 29987250, 2018). "Here, we aimed to investigate the possible influence of lifestyle characteristics and VDR TaqI, BsmI, ApaI and FokI polymorphisms as risk factors for disc degeneration process." (PMID 29467039, 2018). "Other studies showed an association between BsmI, ApaI and TaqI VDR genotypes or alleles and signs of disc degeneration such as bulges, osteophytosis, disc space narrowing or disc herniation." (PMID 27149110, 2016). "Another study in Turks showed that the presence of VDR TaqI mutation was associated with a worse disc degeneration score, and with the development of lumbar disc degeneration." (PMID 27149110, 2016). "Finally, the results reveal novel findings such as increased serum VDR protein levels in LDD patients and a significant increase in VDR promoter methylation, which contributes to advancing our understanding of molecular mechanisms underlying disc degeneration." (PMID 40244065, 2025). "Moreover, the use of the Pfirrmann grading system to categorize disc degeneration stages adds a robust, clinically relevant framework for assessing the severity of degeneration and its potential association with VDR expression." (PMID 40244065, 2025).
disc degeneration (continued). "Additionally, higher VDR promoter methylation in blood was correlated with advanced disc degeneration (p < 0.05), while NP methylation was associated with all grades of degeneration (p < 0.001)." (PMID 40244065, 2025). "Moreover, an association between the mutant allele (C) of VDR gene TaqI polymorphism and disc degeneration is found." (PMID 35919638, 2022). "Moreover, there was a significant association between the mutant allele (C) of VDR gene TaqI polymorphism and disc degeneration." (PMID 35919638, 2022). "Considering a large number of novel case-control studies have been published and the limitations of previous studies, we conducted this meta-analysis in a comprehensive way to drive a more precise estimation of association between VDR TaqI, FokI, and ApaI polymorphisms and disc degeneration risk." (PMID 34011063, 2021). "However, the results of subgroup analyses by ethnicity showed a significant association of VDR FokI mutation with disc degeneration risk in Caucasians (Recessive model, OR with 95%CI 1.301, [1.041, 1.626], Additive model, OR with 95%CI 1.119, [1.006, 1.245])." (PMID 34011063, 2021). "In addition, blood VDR promoter methylation was significantly associated with higher Pfirrmann grades, suggesting a potential link between VDR promoter methylation and the severity of disc degeneration." (PMID 40244065, 2025). "The inheritance patterns of the VDR polymorphism were also evaluated and the TaqI polymorphism exhibited a significant difference in the recessive model (p = 0.042) between groups, whereas two polymorphic alleles (CC) are necessary to predispose a higher risk for disc degeneration." (PMID 29467039, 2018). "The control group exhibited significantly greater NP VDR expression compared to LDD patients with advanced disc degeneration (LDD grades 4 and 5; p = 0.013 and p = 0.045, respectively)." (PMID 40244065, 2025). "Vitamin D receptor is involved in disc degeneration process indirectly, through its function within the chondrocyte." (PMID 29467039, 2018). "Function of vitamin D is meditated by vitamin D receptor (VDR), a steroid nuclear receptor which is located on chromosome 12 with 5.6 kb and it was the first reported gene associated with degenerative diseases of the disc." (PMID 30356314, 2018). "In addition, the control group exhibited significantly higher NP VDR protein levels than the LDD patients with advanced disc degeneration stages (LDD grade 5; p = 0.022, respectively)." (PMID 40244065, 2025). "Additionally, the control group displayed significantly lower serum VDR protein levels than the LDD patients with advanced disc degeneration stages (LDD grades 4 and 5; p = 0.031 and 0.021, respectively)." (PMID 40244065, 2025). "The vitamin D receptor (VDR) gene, situated on chromosome 12q12-q14 and consisting of eight protein-coding and six untranslated exons, has been extensively researched as a potential candidate gene linked to disc degeneration." (PMID 37868452, 2023). "The results of subgroup analyses by ethnicity showed a significant association of VDR TaqI mutation with disc degeneration risk in Asians but not in Caucasians." (PMID 34011063, 2021). "the specific mechanism underlying the relationship between VDR gene polymorphism and disc degeneration risk is still not entirely clear." (PMID 34011063, 2021). "No significant heterogeneity between VDR TaqI polymorphism and risk of disc degeneration was found in all models." (PMID 34011063, 2021). "For these reasons, the use of vitamin D to treat the degenerated disc with homeostatic or regenerative purposes is not suggestable, particularly for patients bearing FF VDR genotype which showed the highest risk of developing degenerative disc diseases." (PMID 29987250, 2018). "However, the results of subgroup analyses by ethnicity showed a significant association of VDR TaqI mutation with disc degeneration risk in Asians but not in Caucasians." (PMID 34011063, 2021).
disc degeneration (continued). "Third, this study also only focused on the blood and NP tissue samples, which may not fully capture the systemic effects of VDR downregulation, or the impact of other tissues involved in disc degeneration." (PMID 40244065, 2025).
multiple myeloma (10 papers, 2014 to 2026). "Vitamin D acts through the vitamin D receptor (VDR), and vitamin D level decreases in multiple myeloma (MM) patients." (PMID 38833040, 2024). "Results from another in vitro study showed that VDR mRNA and protein expression is decreased in a multiple myeloma cells line by EBV." (PMID 32513132, 2020). "Since inhibition of proteasome increases the VDR protein together with higher stability of VDR in the presence of ligand, especially multiple myeloma (MM) patients, treated with proteasome inhibitor bortezomib, might greatly benefit from vitamin D supplementation." (PMID 28427151, 2017).
myopia (10 papers, 2016 to 2025). "Considering the obscure mechanisms underlying the involvement of vitamin D and the VDR in myopia development, it is posited that calcitriol occupies a pivotal role in the genesis of myopia." (PMID 38762668, 2024). "Some studies have indicated variations in the VDR as a potential risk factor for myopia development." (PMID 34168925, 2021). "They identified 5 studies showing the relation between vitamin D level in blood and the risk of myopia and 2 studies investigating changes in vitamin D receptor as a potential risk factor for the development of myopia." (PMID 29576878, 2018). "The f allele produced by the VDR gene Fok1 (exon 2 start codon) may enhance the sex-specific risk of myopia onset and progression in women, particularly those with modest myopia." (PMID 36570139, 2022). "One study reported the association of VDR polymorphisms, rs2853559, with myopia." (PMID 35457041, 2022). "Other researchers also revealed that myopes had a significantly lower blood vitamin D concentration compared with non-myopes, A large population-based study revealed that polymorphisms within vitamin D receptor (VDR) are related to a low-to-moderate degree of myopia." (PMID 30677087, 2019). "The findings of this study identified a reduction in calcitriol and VDR levels during the progression of myopia." (PMID 38762668, 2024). "In this study, we primarily consider the regulatory role of calcitriol through the VDR pathway in the development and progression of myopia." (PMID 38762668, 2024). "Our study confirmed the role of calcitriol and VDR in the onset and progression of myopia." (PMID 38762668, 2024). "Our findings highlight a significant decrease in calcitriol and VDR expressions in myopic guinea pigs and demonstrate that exogenous calcitriol supplementation can halt myopia development, enhancing choroidal and scleral thickness and scleral collagen fiber diameter." (PMID 38762668, 2024). "The VDR gene is located near the loci found to be related to myopia (MYP-3)." (PMID 34168925, 2021). "Interestingly, it has been shown that polymorphisms within vitamin D receptor (VDR) at 12q13.11 and GC at 4q12-13 appear to be associated with low-to-moderate amounts of myopia in white subjects." (PMID 29576878, 2018). "In humans, VDR is involved in retinoid functions of the eye such as accommodation, pupil responses, and aqueous humor production, and may have an indirect and functional role in ocular growth and myopia development." (PMID 27435453, 2016). "Genetic variants in the vitamin D pathway genes appeared not to be related: although SNPs in the VDR and CYP24A1 genes showed some association with AL and myopia, this did not remain after adjustment for multiple testing." (PMID 26955828, 2016). "Prior studys have not conclusively established a link between VDR and myopia." (PMID 38762668, 2024).
pulmonary fibrosis (10 papers, 2009 to 2024). Chronic progressive interstitial lung disorder characterized by the replacement of the lung tissue by connective tissue, leading to progressive dyspnea, respiratory failure, or right heart failure. "Analysis of bulk and single-cell RNA profiling datasets revealed VDR upregulation in lung fibroblasts from patients with pulmonary fibrosis or fibrotic mice, which was validated in lung fibroblasts from bleomycin-exposed mice and bleomycin-treated fibroblasts." (PMID 37627629, 2023). "Collectively, these findings indicate that VDR overexpression results in the inhibition of fibroblast proliferation and differentiation into myofibroblasts during bleomycin-induced lung fibrosis." (PMID 37627629, 2023). "The present study revealed, for the first time, that VDR was specifically upregulated in lung fibroblasts during pulmonary fibrosis." (PMID 37627629, 2023). "Taken together, the bioinformatic analysis and validation results indicated that VDR is specifically upregulated in lung fibroblasts during pulmonary fibrosis." (PMID 37627629, 2023). "To investigate the role of VDR in the progression of pulmonary fibrosis, we first analyzed eight published GEO datasets for VDR expression in lung tissues from UIP/IPF patients." (PMID 37627629, 2023). "Collectively, these findings indicate that VDR activation results in the inhibition of fibroblast proliferation and differentiation into myofibroblasts during bleomycin-induced lung fibrosis." (PMID 37627629, 2023). "We then analyzed 12 published GEO datasets for VDR expression in lung tissues from murine models of bleomycin-induced pulmonary fibrosis." (PMID 37627629, 2023). "We showed, for the first time, that VDR was specifically upregulated in lung fibroblasts during pulmonary fibrosis." (PMID 37627629, 2023). "Since RAS activation also induces TGF-β1, these data confirm that the 1,25(OH)2D3/VDR signaling in the lung protects against lung fibrosis induced by the activation of the RAS." (PMID 34400742, 2021). "Fibroblast VDR upregulation may be recognized as part of a novel self-protective response to limit fibroblast proliferation and activation during pulmonary fibrosis." (PMID 37627629, 2023). "Taken together, these findings suggest that the upregulation of fibroblast VDR may be recognized as part of a novel self-protective response to regulate fibroblast proliferation and activation during pulmonary fibrosis." (PMID 37627629, 2023). "We then examined the effect of VDR agonist on bleomycin-induced pulmonary fibrosis." (PMID 37627629, 2023). "Collectively, this study suggests that fibroblast VDR upregulation may be a self-protective response to limit fibroblast proliferation and activation during pulmonary fibrosis by suppressing the JAK1/STAT3/ER stress pathway." (PMID 37627629, 2023). "Therefore, we conclude that vitamin D/VDR signaling suppresses BLM-induced lung fibrosis by inhibiting the activation of the local RAS in the lung." (PMID 34400742, 2021). "VDR as a regulator of EMT during BLM-induced pulmonary fibrosis may have preventive and therapeutic implications." (PMID 31775746, 2019). "However, whether dysregulation of VDR occurs and contributes to the development of pulmonary fibrosis remains largely unknown." (PMID 37627629, 2023). "However, whether VDR dysregulation contributes to the development of pulmonary fibrosis remains largely unknown." (PMID 37627629, 2023). "However, the role of VDR in the pathogenesis of pulmonary fibrosis remains largely unknown." (PMID 37627629, 2023). "Treatment with vitamin D prevented lung fibrosis by blocking the TGFβ/Smad3 axis, repressing epithelia-mesenchymal transition (EMT), and restoring mRNA levels of the vitamin D receptor (VDR)." (PMID 36835058, 2023). "Thus, it is speculated that VDR may be a regulator of EMT during BLM-induced pulmonary fibrosis." (PMID 31775746, 2019).
pulmonary fibrosis (continued). "Application of vitamin D in conditions of bleomycin-induced pulmonary fibrosis contributed to a decrease in the expression levels of mRNA collagen type I, type III, and smooth muscle actin with the restoration of the bleomycin-induced decrease in VDR mRNA expression." (PMID 39201632, 2024).
Salmonella Infections (10 papers, 2012 to 2023). Infections with bacteria of the genus SALMONELLA. "VDR-null mice have increased IL-6 production after Salmonella infection and VDR deletion is associated with elevated NF-κB in intestinal epithelia." (PMID 23240054, 2012). "Salmonella infection induced VDR and AhR mRNA expression in the cecal tissue of mice and, the combination of PP and VD3 synergistically enhanced both mRNA expression." (PMID 36672703, 2023). "Salmonella infection induced VDR mRNA expression (normalized to GAPDH) in Caco-2 cells after one-hour infection, which was synergically enhanced using a combination of butyrate and 1,25D3." (PMID 34680413, 2021). "Salmonella infection induced VDR mRNA expression (normalized to GAPDH) in SW480 cells, which was synergistically enhanced by combination of Bifidobacterium longum and 1,25D3." (PMID 34576700, 2021). "A change in VDR localization in colonic epithelial cells has also been reported during Salmonella infection." (PMID 34445577, 2021). "In addition, VDR-/- mice had an increased bacterial burden and mortality, more easily detectable levels of IL-6 and elevated NF-κB activity in intestinal epithelia after Salmonella infection." (PMID 26172950, 2015). "AhR and VDR proteins were present at significantly increased levels in cecal mucosa in Salmonella colitis through the treatment of PP and VD3, compared with the Salmonella infection only." (PMID 36672703, 2023). "Interestingly, recent studies demonstrated a link between downregulation of VDR and overexpression of CLDN2 in Salmonella infection." (PMID 34445577, 2021).